CLDN5 (claudin 5)
Diseases named in the same sentence as CLDN5 in open-access papers (continued):
Sharing a sentence is not in itself a finding about the gene and the disease.
multiple sclerosis (19 papers, 2015 to 2025). A progressive autoimmune disorder affecting the central nervous system resulting in demyelination. "Blood CLDN-5 levels are elevated in patients with multiple sclerosis, and loss of CLDN-5 was accompanied by BBB breakdown in a mouse model of autoimmune encephalomyelitis." (PMID 38338697, 2024). "For instance, in multiple sclerosis, decreased expression or reorganization of junctional proteins including claudin-5, occludin, ZO-1 and VE-cadherin has been associated with loss of BBB integrity and increased transmigration of leukocytes." (PMID 35025943, 2022). "Claudin-5 is the most enriched tight junction protein in the blood–brain barrier and its dysfunction is associated with neurodegenerative disorders such as AB, multiple sclerosis and some psychiatric disorders." (PMID 41516246, 2025). "In multiple sclerosis patients, treatment with glucocorticoid lowered mRNA and protein levels of claudin-5 and a significant correlation was found between increased levels of leukocyte claudin-5 protein and multiple sclerosis disease activity." (PMID 30691500, 2019). "In support of this novel role for claudin-5, peripheral blood leukocytes isolated from patients with multiple sclerosis as well as healthy controls expressed claudin-5 with elevated levels in patients experiencing disease relapse." (PMID 30691500, 2019). "Dysregulations of claudin-5 as well as other junctional proteins are known to be a key event in the pathogenesis of a range of brain diseases, including inflammatory diseases, such as multiple sclerosis (MS)." (PMID 37185751, 2023). "In addition, claudin-5 remodeling occurs at sites of leukocyte transmigration in both physiological and pathological conditions such as Multiple Sclerosis and mislocalization of claudin-5 occurs in a mouse model of oxygen induced retinopathy." (PMID 34867185, 2021). "Dephosphorylated occludins were detected in brain endothelial cells and in an experimental autoimmune encephalomyelitis model that mimics multiple sclerosis while a phosphorylation in threonine 207 of claudin-5 at the site of the carboxy-terminus altered BBB integrity." (PMID 30201915, 2018). "In experimental autoimmune encephalomyelitis, a well-characterized model of multiple sclerosis changes in claudin-5 immunostaining in brain vessels were evident at a very early disease stage, while the initially preserved occludin pattern showed alterations at more advanced stages." (PMID 26834555, 2015). "Furthermore, the activation of the RhoA protein induces an increased permeability mediated by the phosphorylation in serine-threonine of occludins, claudin-5, and ZO-1, which, in turn, triggers the migration of lymphocytes as clearly demonstrated in multiple sclerosis." (PMID 30201915, 2018). "Claudin-5 expression in brain tissue significantly increased after traumatic brain injury, and the down-regulation of claudin-5 expression often accompanied by the increased permeability of BBB in many experimental animal models of traumatic and ischemic brain injury and multiple sclerosis." (PMID 27833554, 2016).
Sepsis (19 papers, 2018 to 2024). Sepsis is defined as life-threatening organ dysfunction caused by a dysregulated host response to infection. "Conversely, we have found that in sepsis, Claudin-5 decreases in a SOX18-dependent manner leading to loss of barrier function and increased permeability." (PMID 36620216, 2022). "The integrity of the intestinal barrier, assessed by the expression of the tight junction proteins ZO-1, Occludin, and Claudin-5, was compromised in the sepsis group but was preserved by the ghrelin and Fer-1 treatment." (PMID 39857660, 2024). "In human brain tissue samples from deceased patients with sepsis, a remarkable downregulation of TJ proteins (occludin, claudin-5 and ZO-1) was found in BMVECs, demonstrating impaired BBB integrity." (PMID 36817492, 2023). "In sepsis‐induced lung injury, there is abnormal decrease in the expression of ZO‐1, Claudin 5, and Occludin, which are involved in lung vascular permeability." (PMID 36169256, 2022). "Disrupted expression and localization of tight junction components are observed in Crohn's disease and sepsis, with the upregulation of pore-forming claudin-2 and downregulation of sealing claudin-5 in both cases." (PMID 33579694, 2021). "Mechanistically, claudin-2 and junctional adhesion molecule (JAM)-A are increased by sepsis, whereas claudin-5 and occludin are decreased by sepsis." (PMID 30923621, 2019). "Collectively, these studies demonstrate that serum levels of ZO-1, occludin, zonulin, and claudin-5 are elevated in sepsis." (PMID 30259344, 2018). "They found that occludin and claudin-5 decreased due to sepsis." (PMID 38152336, 2023). "In addition, human brain tissues of patients with decreased sepsis showed that the TJ proteins occludin, claudin-5, VE-cadherin and zonula occludens-1 (ZO-1) in microvascular endothelial cells were downregulated, illustrating BBB dysfunction." (PMID 37474902, 2023). "During sepsis-induced damage to the blood-gas barrier, there is obvious attenuation and translocation of the tight junction proteins (including ZO-1, Claudin 5 and Occludin) in the alveolar epithelial cell membrane, demonstrating that the tight junctions are disrupted." (PMID 36093187, 2022). "In sepsis-induced kidney injury, claudin-5 may be increased and ZO-1 decreased in endothelial cells of biopsy specimens." (PMID 30259344, 2018). "We examined the expression of the tight junction protein claudin 5 in the heart and detected lower claudin 5 expression with lactate treatment than septic control mice, indicating that lactate exerts an additive effect by impairing tight junctions in the myocardium after sepsis." (PMID 36256626, 2022). "In a study involving 51 sepsis patients, plasma levels of occludin (OCLN), claudin-5 (CLDN-5), zonula occludens-1 (ZO-1), PCT, and lactate were evaluated." (PMID 39201697, 2024). "EC permeability was related to other genes, such as, Cldn5 (claudin 5) and Pecam-1/CD31 (platelet EC adhesion molecule), also significantly upregulated in septic capEC, suggesting that sepsis induces gene expression related to capillary permeability." (PMID 34638535, 2021). "The present results have shown that the expression of tight junctional proteins such as occludin, claudin-5, and ZO-1 was decreased in the lung tissues of CLP-induced sepsis rats when compared with the sham group." (PMID 30150933, 2018). "This suggests that patients with sepsis-induced ARDS may already be experiencing a decreased expression of SOX18 and Claudin-5 before the initiation of mechanical ventilation." (PMID 36620216, 2022). "Interestingly, rats challenged with cecal ligation and puncture (as a model of sepsis) showed increased BBB permeability to Evans Blue brain staining and reduced endothelial claudin-3 and claudin-5 levels, effects that were ameliorated by the cholesterol-lowering drug simvastatin." (PMID 30687711, 2018).
diabetes (18 papers, 2015 to 2026). "BHB treatment can inhibit HDAC3 to promote claudin-5 generation and antagonize diabetes-associated cardiac microvascular hyperpermeability." (PMID 35409148, 2022). "It was found that SPL treatment prevented diabetes-induced loss of cldn-5 in GL, and cldn-2 and occldn in PT evaluated by IB." (PMID 28493961, 2017). "Decreased glomerular expression of cldn-5 has been associated with diabetes-induced proteinuria." (PMID 28493961, 2017). "In this respect, SPL also decreased diabetes-induced oxidative stress in GL which may be associated to the preservation of cldn-5 and decreased proteinuria found in the DBT+SPL group." (PMID 28493961, 2017). "Treatment of diabetic rats with TNFSF15 prevented the decrease in claudin-5, occludin, and ZO-1 protein levels caused by diabetes (95.8% ± 10.6%, 85.4% ± 9.2% and 94.1% ± 11.7% of the control, respectively), indicating that TNFSF15 mediates the expression of TJPs." (PMID 27120595, 2016). "In agreement, HG and AGE drive BBB disruption in diabetes through increased Cldn5 and occludin expression, highlighting BBB protection as a potential therapeutic strategy to prevent diabetes-associated cognitive decline." (PMID 40940757, 2025). "The impact of diabetes on the tight junction proteins claudin-5, occludin, and ZO-1 was assessed in retinal wholemounts and homogenates by immunofluorescence and Western blot, respectively." (PMID 40898311, 2025). "BHB inhibits HDAC3 and leads to acetylation of H3K14 in the Claudin-5 promoter, thereby promoting Claudin-5 production and antagonizing diabetes-related cardiac microvascular hyperpermeability." (PMID 36172354, 2022). "We previously studied the impact of diabetes on renal cldns expressions, and described that diabetes decreases the expression of cldn-5 in glomeruli (GL), and cldn-2 and occldn in proximal tubules (PT), in an oxidative stress-dependent way." (PMID 28493961, 2017). "In our previous studies, we found that diabetes decreases the expression of cldn-5 in GL and cldn-2 and occldn in PT, and induces the expression of cldn-4 and -8 in DT." (PMID 28493961, 2017). "In the current work, we observed that diabetes decreased retinal occludin and claudin-5 levels in nine-month-old rats." (PMID 28367226, 2017). "Diabetes (DM) rats had significant decrease in miR-126, claudin-5, occluding, and ZO-1 expression and worsened blood retinal barrier." (PMID 27999452, 2016). "TNF-α altered retinal vascular permeability in diabetes through down-regulation of ZO-1 and claudin-5 protein and mRNA, which is mediated by NF-κB activation." (PMID 25617421, 2015). "In diabetes, increased BRB permeability is associated with reduced expression of tight junction (claudin-5, ZO-1, and occludin) and adherens (VE-cadherin) proteins." (PMID 25918731, 2015). "Recurrent hypoglycaemia in the absence of diabetes was associated with changes in a small subset of genes associated with endothelial integrity, β-adrenergic signalling and heart failure, including Cldn5, Akap12, Nr4a2 and Adamts4." (PMID 41212210, 2026). "Similarly, endothelial-specific loss of Akt1 promotes nuclear accumulation of β-catenin, which represses Cldn5 transcription, disrupts barrier function, and facilitates prostate cancer cell transmigration, lung metastasis, and diabetes-enhanced carcinogenesis." (PMID 40940757, 2025). "However, CTRP3 preserves iBRB function in NPDR by preventing diabetes-suppressed Occludin and Claudin-5 (tight junction protein) expression in an AMPK-dependent manner." (PMID 35269401, 2022). "However, TWOD and CaD treatment significantly attenuated the alterations in occludin and claudin-5 expressions induced by diabetes." (PMID 28367226, 2017). "Thus, diabetes damaged the TJ protein, and occludin and claudin-5 injuries accelerated the development of diabetes." (PMID 28367226, 2017). "It is interesting that diabetes-induced loss of cldn-5 protein is not related to its mRNA levels, because they were not altered." (PMID 28493961, 2017).
diabetes (continued). "In the current study, we report that AMPK activation in the retina was inhibited in diabetes-induced NPDR, consequently suppressing the crucial molecules Occludin and Claudin-5 in iBRB." (PMID 35269401, 2022). "Additionally, we explore the mRNA levels of these proteins, it was found that diabetes did not change cldn-5 and occldn expressions, thus suggesting that loss of both proteins is consequence of post translational modifications." (PMID 28493961, 2017). "Diabetes decreases the amount of occludin and claudin-5, but not the content of ZO-1." (PMID 26389948, 2015).
colitis (17 papers, 2011 to 2025). Inflammation of the colon. "Mice deficient in VDR show reduced Cldn5 mRNA expression, leading to increased intestinal permeability and elevated risk of colitis-associated tumorigenesis." (PMID 40940757, 2025). "In both inflammatory bowel disease (IBD) patients and dextran sodium sulfate (DSS)-induced colitis models, elevated interleukin-21 (IL-21) levels are associated with Cldn5 downregulation, mediated by upregulation of miR-423-5p." (PMID 40940757, 2025). "Moreover, colitis has been associated with decreased transcription of ZO-1 (Tjp1) and claudin-5 (Cldn5) in the brain." (PMID 34983592, 2022). "The positively correlated status of VDR and claudins, such as claudin-5 and -15, could be potentially applied to risk assessment, early detection, and prevention of colitis and colitis-associated colon cancer." (PMID 35406694, 2022). "Studies have also found activation of microglial cells and decrement in occludin and claudin-5 expression in the brain tissue after DSS-induced colitis." (PMID 35011101, 2022). "Western blot analysis showed that the expressions of ZO-1 and claudin-5 were significantly downregulated in DSS-induced colitis mice compared with the control group on day 7, day 14, and day 21, suggesting the dysfunction of epithelial barrier." (PMID 31989391, 2020). "Anti-IL-21 administrated prevented DSS-simulative colitis via recovering claudin-5 expression in the human colonic epithelial cells." (PMID 32855360, 2020). "Treated with CXCR4 antagonist AMD3100 significantly promoted colonic claudin-1, claudin-3, claudin-5, claudin-7 and claudin-8 expressions, and also decreased colonic claudin-2 in colitis mice." (PMID 22073304, 2011). "The immunostaining of claudin-5 was decreased in intensity in colitis mice, and enhanced when treated with CXCR4 antagonist AMD3100." (PMID 22073304, 2011). "The expressions of colonic claudin-1, claudin-3, claudin-5, claudin-7 and claudin-8 in colitis mice were markedly decreased as compared with control mice." (PMID 22073304, 2011). "Furthermore, the oat and oat bran intervention groups were able to increase the expression levels of Claudin-1 and Claudin-5 genes in the colon of DSS-induced colitis mice." (PMID 39770986, 2024). "Moreover, in the present study, we found that treated with CXCR4 antagonist AMD3100 significantly promoted colonic claudin-1, claudin-3, claudin-5, claudin-7 and claudin-8 expressions, and also decreased colonic claudin-2 in colitis mice." (PMID 22073304, 2011). "They increased TNBS-suppressed claudin-1 and mucin barrier protein mucin-2 expression in the colon and claudin-5 in the hippocampus, resulting in the attenuation of TNBS-induced colitis and neuroinflammation." (PMID 35889931, 2022). "In rats with TNBS-induced colitis, diet supplementation with grape peel powder rich in polyphenols and fiber or with fish oil rich in ω-3 PUFAs strongly upregulated the ZO-1, CLDN1, CLDN5 and CLDN8 protein expressions in colon." (PMID 33806347, 2021). "SSP significantly improved the clinical symptoms of colitis in rats and reduced the expression of p-RhoA, ROCK1, PI3K, and Akt in the colon mucosa, while it increased the expression of p-Rac and related proteins (Claudin-5, JAM1, VE-cadherin, and Connexin 43)." (PMID 34925530, 2021). "The protein expression levels of ZO-1, claudin-5, and occludin were markedly decreased in DSS-induced colitis mice than in normal controls but they were slightly increased after HnAb administration compared with vehicle (IgY)-treated DSS-induced colitis mice." (PMID 33193406, 2020). "In this paper, tight junction proteins claudin-5 and ZO-1 were notably downregulated in mice after DSS treatment, and further H&E identically supported our findings, indicating the impairment of intestinal mucosal barrier in DSS-induced colitis mice." (PMID 31989391, 2020).
colitis (continued). "The mRNA expression levels of ZO-1 (P<0.001) and claudin-5 (P<0.01), but not occludin (P=0.587), were significantly higher in colonic tissues of HnAb-treated DSS-induced colitis mice than IgY-treated DSS-induced colitis mice." (PMID 33193406, 2020).
Anxiety (16 papers, 2018 to 2026). Intense feelings of nervousness, tension, or panic often arise in response to interpersonal stresses. "Other studies showed that social isolation in female juvenile mice caused anxiety-like behaviors in adult mice, and this was linked to a decrease in claudin-5 expression and BBB breakdown in the amygdala." (PMID 39367201, 2025). "Mechanistically, this may be through a loss of tight junction proteins, as previous studies have shown that a loss of these proteins (e.g., Cldn5) induced anxiety-like behaviors." (PMID 38792656, 2024). "Finally, down-regulation of Claudin-5 induced anxiety-like behaviors in group-housed females and overexpression of Claudin-5 with adeno-associated virus in the amygdala to restore BBB integrity decreased subsequent anxiety-like behaviors." (PMID 36051441, 2022). "In preclinical studies, suppression of claudin-5 protein induces anxiety and depressive-like behavior, whereas administration of microbial major SCFAs or the bacteria which produces them restores its expression." (PMID 38409102, 2024). "In female mice, viral-mediated downregulation of Claudin-5 is sufficient to induce anxiety-like behaviors, while overexpression of Claudin-5 prevents these behavioral deficits induced by social isolation." (PMID 36051441, 2022). "The effects of knockdown of Claudin-5 on anxiety states under the condition of subthreshold social isolation stress should also be evaluated." (PMID 36051441, 2022). "Using an inducible ‘knockdown’ mouse model, we further link claudin-5 suppression with psychosis through a distinct behavioural phenotype showing impairments in learning and memory, anxiety-like behaviour and sensorimotor gating." (PMID 28993710, 2018). "Similarly, in female rodents, chronic social-defeat stress (CSDS) can induce loss of Claudin-5 (Cldn5), the dominant tight junction in BBB, in the PFC and NAc leading to BBB leakiness in these brain areas and promoting anxiety and depressive-like behaviors." (PMID 40650814, 2025). "Altogether, these data suggest that enhancement of Claudin-5 in the amygdala could prevent isolation-induced anxiety-like behaviors and may serve as a potential therapeutic target for emotional deficits, particularly in female mice." (PMID 36051441, 2022). "In this study, down-regulation of Claudin-5 expression in the amygdala of female mice could induced anxiety-like behaviors." (PMID 36051441, 2022). "Here, to further determine the role of BBB tight junctions in anxiety, we investigated whether up-regulation of Claudin-5 expression in the amygdala could prevent isolation-induced anxiety-like behaviors in females." (PMID 36051441, 2022). "In contrast, overexpression of Claudin-5 in the amygdala of female mice prevented anxiety-like behavior induced by social isolation, indicating that BBB damage in the amygdala of female mice may be a key factor of anxiety-like behaviors induced by chronic social isolation." (PMID 36051441, 2022). "Given the findings that decreased expression of Claudin-5 in the amygdala is linked to isolation-induced anxiety-like behaviors in females, we further investigated whether down-regulation of Claudin-5 in the amygdala could induce anxiety-like behaviors in group-housed female mice." (PMID 36051441, 2022). "As in OCD studies where anxiety symptoms can be detected, this study suggested that increased neuroinflammation in PD may increase BBB permeability and that claudin-5 levels may increase in a compensatory manner secondary to the increase in BBB permeability." (PMID 41458033, 2025). "Our results confirmed that Claudin-5 down-regulation in the amygdala can induce anxiety-like behaviors without social isolation." (PMID 36051441, 2022).
Anxiety (continued). "Although the role of pre-treatment claudin-5 level in predicting PD diagnosis was examined using ROC analysis in this study, specificity for PD diagnosis cannot be determined based on ROC analysis alone without including various psychiatric disorders, such as anxiety and mood disorders." (PMID 41458033, 2025).